ICAM1 (intercellular adhesion molecule 1)
Description:
Cell adhesion molecule that functions as a receptor ligand of the signaling receptor ITGAL:ITGB2/LFA-1 (lymphocyte-function associated (LFA) molecule 1) ensuring leukocyte cell-cell adhesion, by providing a calibrated system to namely adjust T-cell killing to the antigen stimulation strength. Also functions as a ligand receptor of the signaling receptor ITGAM:ITGB2/MAC-1 ensuring adhesion between stimulated neutrophils and stimulated endothelial cells. During leukocyte trans-endothelial migration, ICAM1 engagement promotes the assembly of endothelial apical cups through ARHGEF26/SGEF and RHOG activation. Promotes cell aggregation in epithelial cells through interaction with MUC1. (Microbial infection) Acts as a receptor for major receptor group rhinovirus A-B capsid proteins. (Microbial infection) Acts as a receptor for Coxsackievirus A21 capsid proteins. (Microbial infection) Upon Kaposi's sarcoma-associated herpesvirus/HHV-8 infection, is degraded by viral E3 ubiquitin ligase MIR2, presumably to prevent lysis of infected cells by cytotoxic T-lymphocytes and NK cell.
Synonyms: CD54; BB2; P3.58
Tractability: Small molecule: a high-quality ligand is known; it belongs to a druggable protein family. Antibody: a drug acting on it is in phase 2 or 3 trials; its Gene Ontology location is reachable by antibodies, with high confidence; UniProt predicts a signal peptide or a membrane-spanning region; the Human Protein Atlas places it where antibodies can reach. PROTAC: UniProt records ubiquitination sites on it; ubiquitination databases record sites on it; its protein half-life has been measured; a small molecule that binds it is known.
Target class: Adhesion
Gene: Protein-coding gene on chromosome 19 (10,271,093 to 10,286,615, forward strand). Ensembl gene ENSG00000090339.
Subcellular location: Cell membrane
Subcellular location (Human Protein Atlas): Plasma membrane; Cytosol; Vesicles
Pathways (Reactome):
Immune System: Immunoregulatory interactions between a Lymphoid and a non-Lymphoid cell; Interferon gamma signaling; Interleukin-10 signaling; Interleukin-4 and Interleukin-13 signaling
Extracellular matrix organization: Integrin cell surface interactions
Gene Ontology:
Molecular function: integrin binding; protein binding; receptor ligand activity; signaling receptor activity; transmembrane signaling receptor activity
Biological process: adhesion of symbiont to host; cell adhesion; cell-cell adhesion mediated by integrin; cellular response to amyloid-beta; establishment of endothelial barrier; leukocyte adhesion to vascular endothelial cell; leukocyte cell-cell adhesion; leukocyte migration; membrane to membrane docking; negative regulation of endothelial cell apoptotic process; negative regulation of extrinsic apoptotic signaling pathway via death domain receptors; positive regulation of cellular extravasation; positive regulation of ERK1 and ERK2 cascade; receptor-mediated virion attachment to host cell; T cell activation via T cell receptor contact with antigen bound to MHC molecule on antigen presenting cell; heterophilic cell-cell adhesion; regulation of leukocyte mediated cytotoxicity; cell-cell adhesion; cellular response to oxygen-containing compound; immune effector process; immune response; signal transduction
Cellular component: cell surface; extracellular exosome; extracellular matrix; extracellular region; focal adhesion; membrane; plasma membrane; external side of plasma membrane; immunological synapse; membrane raft
Genetic constraint (gnomAD): Loss-of-function variants: 28 observed, 43.81 expected, observed/expected ratio (o/e) 0.64, 90% interval 0.47 to 0.88. The upper end of that interval is the gene's LOEUF score, 0.88, which puts it in group 3 of 6, group 1 being the genes least tolerant of losing a copy. Missense variants: 637 observed, 720.24 expected, observed/expected ratio (o/e) 0.88, 90% interval 0.83 to 0.94. Synonymous variants: 304 observed, 320.91 expected, observed/expected ratio (o/e) 0.95, 90% interval 0.86 to 1.04.
Homologues: Orthologues: chimpanzee ICAM1 (96% identical), macaque ICAM1 (85% identical), rabbit ICAM1 (64% identical), dog ICAM1 (62% identical), pig ICAM1 (54% identical), mouse Icam1 (53% identical), rat Icam1 (52% identical). Paralogues in human: ICAM3 (47% identical), ICAM5 (46% identical), ICAM2 (15% identical), ICAM4 (13% identical).
Diseases named in the same sentence as ICAM1 in open-access papers:
ICAM1 is named in the same sentence as 764 diseases in open-access papers, as found by Europe PMC text mining. Sharing a sentence is not in itself a finding about the gene and the disease. The quoted sentences say what the papers report.
atherosclerosis (610 papers, 2007 to 2026). A disease characterized by the build-up of fatty material and calcium deposition in the arterial wall resulting in partial or complete occlusion of the arterial lumen. "Conversely, deficiency of ICAM-1 is protective against atherosclerosis and associated with substantially diminished atheromatous plaque burden in vivo." (PMID 40630903, 2025). "The expression of VCAM-1 and ICAM-1, which are localized to the endothelium in atherosclerosis-susceptible arterial regions, precedes monocyte recruitment and forms important links between inflammation and atherosclerosis." (PMID 39113913, 2024). "Elevated levels of ICAM1 have been associated with cardiovascular diseases such as atherosclerosis and heart failure." (PMID 39243097, 2024). "Meanwhile, genetic deficiencies of MCP-1, VCAM-1, and ICAM-1 have been believed to be related with decreased atherosclerosis." (PMID 36627567, 2023). "In vivo, aldosterone promotes vascular ICAM1 mRNA expression and associated atherosclerosis that is prevented in ICAM1-deficient ApoE-KO mice." (PMID 37610001, 2023). "Of note, ICAM-1 expression is not only an EC activation marker, but it also mediates monocyte recruitment, vascular inflammation, and atherosclerosis, since ICAM-1 deficiency in ApoE–/– mice reduces atherosclerotic lesions." (PMID 36394956, 2023). "The role of ICAM-1 is also suggested by the association of polymorphisms of the ICAM1 gene with atherosclerosis." (PMID 37237555, 2023). "Oxidized low-density lipoprotein (oxLDL), a known risk factor for atherosclerosis, activates the transcription of adhesion molecules (ICAM-1) in endothelial cells." (PMID 35246513, 2022). "Several studies reported that CVD patients with diabetes and hypertension who possess high serum levels of ICAM-1 are associated with atherosclerosis and coronary artery calcified plaque (CAC) progression." (PMID 36361845, 2022). "ICAM-1 is a vital factor in the pathogenic mechanism of atherosclerosis and has a significant function in recruiting mononuclear cells into the basement membrane of the vasculature." (PMID 36440000, 2022). "In summary, our study shows that endothelial SRC-3 deficiency or pharmacological inhibition prevents atherosclerosis development by decreasing endothelial ICAM-1 expression, resulting in the inhibition of macrophage recruitment." (PMID 36263184, 2022). "On the contrary, ICAM-1 deficiency prevents the progression of atherosclerosis, macrophage accumulation in the plaque, and vascular inflammation in mice." (PMID 35246513, 2022). "V55 reduced expression of Icam-1, Wnt5a and Mmp7 (associated to inflammation and tissue destruction in periodontitis) and Scd1, Scd2, Egf1 (correlated to atherosclerosis)." (PMID 35631379, 2022). "In endothelial cells, ICAM-1 can be transcriptionally activated by oxLDL which is a known risk factor for atherosclerosis." (PMID 35246513, 2022). "We will detect changes in ICAM-1 and IL-8, which have been identified as early indicators of atherosclerosis and vascular endothelial damage caused by PM2.5, to explain physiological mechanisms of PM2.5 damage to the vascular endothelium." (PMID 35209939, 2022). "A mouse model of atherosclerosis injected with MB associated with biotinylated antibody targeting ICAM1 and the angiogenesis inhibitor Endostar (MBie) inhibited atherosclerotic plaque in a mouse model of atherosclerosis in the presence of UTMB." (PMID 35163604, 2022). "ICAM-1 in the blood has been recognized as a marker of vascular inflammation in atherosclerosis; it has been shown to predict cardiovascular risk and future cardiovascular disease." (PMID 36035922, 2022). "Higher levels of VCAM-1/ICAM-1 are associated with atherosclerosis which take part in the disease progression as ICAM-1 help in transmigration of the immune cells in the sub-endothelial space." (PMID 33925294, 2021). "For instance, mice with mutated VCAM-1 and ICAM-1 have decreased atherosclerosis compared to control mice." (PMID 34291056, 2021).
atherosclerosis (continued). "Other atherosclerosis risk factors, such as Mmp13, M-CSF, sdf-1α, and Integrinβ2, are also targets of miR-130a-3p possibly; however, only Mmp13 and ICAM-1 were upregulated in accordance with downregulated miR-130a-3p." (PMID 32855961, 2020). "Soluble ICAM-1 levels reflect ICAM-1 expression on activated endothelial cells and are associated with the degree of atherosclerosis." (PMID 32121255, 2020). "Studies have shown that ICAM-1 and VCAM-1 levels are elevated in patients with atherosclerosis, and the baseline ICAM-1 level is reportedly significantly associated with incident myocardial infarction and carotid atherosclerosis." (PMID 32433661, 2020). "Intercellular adhesion molecule-1 (ICAM-1) is a proinflammatory and proatherogenic cytokine which is associated with atherosclerosis, insulin resistance, and cardiovascular disease (CVD)." (PMID 31629408, 2019). "Intercellular adhesion molecule-1 (ICAM-1) is considered as one of the important risk factors involved in atherosclerosis progression." (PMID 30134788, 2018). "There is now a substantial body of evidence to suggest thatincreased levels of serum ICAM-1 are associated with the occurrence of atherosclerosis, myocardial infarction, peripheral artery disease and diabetes mellitus type 2." (PMID 29696063, 2018). "Involvement of ICAM-1 in the progression of atherosclerosis in the ApoE-deficient mice model has been previously reported." (PMID 30524759, 2018). "Increased transcript levels of markers associated with atherosclerosis or cardiovascular impairments (Edn1, Selp, Alox5, and Icam1) further indicate plausible detrimental effects of CNP exposure on aortic tissue at 24 h post inhalation." (PMID 28637465, 2017). "Previously in the same populations, we measured several circulating biomarkers related to atherosclerosis, and reported that chronic exposure to arsenic was positively associated with ICAM-1, VCAM-1 levels, and negatively associated with HDL-C." (PMID 28399171, 2017). "MCP-1 and ICAM-1 are both considered to be robust markers of inflammation that are associated with atherosclerosis and their expression is known to be induced by IFN-γ." (PMID 26950833, 2016). "An increased level of the ICAM 1 molecule is associated with numerous inflammatory diseases including atherosclerosis of carotid arteries." (PMID 27090396, 2016). "The major risk factors of atherosclerosis significantly improved the level of ICAM-1 or VCAM-1 expression in vascular intima." (PMID 26398523, 2015). "Decreased expression of CD80 has been found to result in the inactivation of T cells, while decreased expression of ICAM-1 results in a reduction in leukocyte rolling; both are associated with the progression of atherosclerosis." (PMID 26622474, 2015). "In the present study, we found that loss of CCN3 was correlated with VCAM-1 and ICAM-1 expression in atherosclerosis, and the overexpression of CCN3 significantly inhibited the expression of these genes." (PMID 24722330, 2014). "Interleukin (IL)-6 is associated with atherosclerosis, as it induces intercellular adhesion molecule-1 (ICAM-1), which leads to the accumulation of leukocytes and inflammatory cells in vessel lumina and modulates SMC proliferation." (PMID 24551856, 2014). "Previous studies stated that there is a rise of ICAM-1 levels especially in metabolically poorly controlled diabetic patients and those are at high risk of atherosclerosis and vascular complications." (PMID 25287126, 2014). "It is assumed that ICAM-1, VCAM-1 and E-/P-selectin take part in the causal pathway leading to atherosclerosis as selectins mediate rolling of leukocytes along the endothelium and ICAM-1 and VCAM-1 lead to adhesion and transendothelial migration of leukocytes." (PMID 24276320, 2013). "An SGEF-based pharmacological prevention strategy is further supported by studies showing that ICAM-1 deficiency also results in reduced atherosclerosis." (PMID 23372835, 2013).
atherosclerosis (continued). "In particular, high serum levels of ICAM-1 represent an independent risk factor for atherosclerosis and a predictor of future CV events." (PMID 22962622, 2012). "Studies in low-density lipoprotein (LDL) receptor- or APOE-knockout mice have shown that a deficiency of ICAM-1 or MCP-1 reduced atherosclerosis." (PMID 17963506, 2007). "ICAM-1 expression was lowered by 8 weeks of treadmill training (60 min/day, 5 days/week) in diabetic rats and swimming (60 min/day, 5 days/week) in rats predisposed to atherosclerosis." (PMID 39742025, 2024). "They found that trans-lycopene from tomato juice may reduce CVD risk by lowering the concentration of inflammatory molecules associated with atherosclerosis, such as adhesion molecules ICAM-1, VCAM-1, and IL-8." (PMID 39599645, 2024). "Moreover, elevated ICAM1 and other EC adhesion molecules associated with disease severity have been described in chronic cardiovascular diseases, including atherosclerosis and coronary heart disease." (PMID 39739157, 2024). "In addition, VCAM1, NCF2, RAC2, MMP9, and ICAM1 were associated with fluid shear stress and atherosclerosis." (PMID 38640295, 2024). "ICAM-1 is an independent risk factor for atherosclerosis and developing coronary heart disease." (PMID 36717689, 2023). "Circulating soluble ICAM-1 is a biochemical marker associated with atherosclerosis progression." (PMID 36767947, 2023). "A thorough investigation of ICAM1 gene polymorphisms associated with atherosclerosis is warranted." (PMID 37237555, 2023). "Knockdown of ICAM-1 in apolipoprotein E (ApoE−/−)-deficient mice led to reduced vascular lesion size and has been implicated to exert a more important function in the progression of atherosclerosis." (PMID 37830604, 2023). "Although previous studies have indicated that the identification of the ICAM1 gene variant might be predictive of atherosclerosis in CVD patients, here we show that the variant may predict HCL and therefore may be used in the prevention of ASCVD." (PMID 35282277, 2022). "Atherosclerosis and atherogenic diet-mediated inflammation are also prevented by its anti-inflammatory impact, which also appears to be caused by reducing the activation of inflammatory markers, such as NF-κB, ICAM-1, and pro-inflammatory cytokines." (PMID 36422550, 2022). "Previous studies have confirmed that ICAM-1 plays a vital role in the pathogenesis of atherosclerosis and the influences of many risk factors may be also mediated through their effects on ICAM-1." (PMID 35845572, 2022). "Molecules such as E-selectin and P-selectin, vascular cell adhesion molecule-1 (VCAM-1), and intercellular adhesion molecule-1 (ICAM-1) are predictors of endothelial dysfunction, representing an early marker of atherosclerosis events associated with cardiovascular risk factors." (PMID 36555645, 2022). "Similarly, Icam1 has also been implicated in tumor metastasis in the lung, and both Icam1 and Vcam1 contribute to atherosclerosis, which are diseases associated with cigarette smoking." (PMID 36613693, 2022). "This study aimed to determine the relationships between severity of OSA, degree of steatosis in NAFLD and cardiovascular risk via CIMT and atherosclerosis markers ie intracellular adhesion molecule-1 (ICAM-1) an Lipoprotein-a (Lp(a)) in a group of patients with OSA." (PMID 34191823, 2021). "Thus, an increased concentration of circulating ICAM-1 is often associated with inflammatory diseases, atherosclerosis, and the brain lesions that occur with MS." (PMID 34239993, 2021). "Moreover, Nrf2-HO1 signaling is linked to ICAM-1 expression in a mouse atherosclerosis model, in THP-1 macrophages, and HaCaT cells." (PMID 32121422, 2020). "Western blotting analysis showed that the protein expression levels of ICAM-1, an atherosclerosis-associated endothelial-leukocyte adhesion molecule, and MCP-1, an important chemotactic factor, were significantly higher in PA-treated HUVECs than in the control and DMSO treated HUVECs." (PMID 32300482, 2020).